RNY4P10 (RNY4 pseudogene 10)
Gene: Miscellaneous RNA gene on chromosome 6 (33,199,601 to 33,199,696, forward strand). Ensembl gene ENSG00000202441.
Homologues: Orthologues: chimpanzee Y_RNA (100% identical). Paralogues in human: RNY4 (92% identical), RNY4P7 (91% identical), RNY4P14 (90% identical), RNY4P6 (90% identical), Y_RNA (90% identical), RNY4P13 (89% identical), RNY4P27 (89% identical), Y_RNA (89% identical), RNY4P24 (88% identical), RNY4P25 (88% identical), RNY4P3 (88% identical), Y_RNA (88% identical), and 90 more.